G2E3 (G2/M-phase specific E3 ubiquitin protein ligase)
Description:
E3 ubiquitin-protein ligase involved in the establishment of constitutive heterochromatin at pericentric regions by catalyzing histone H3 'Lys-14' monoubiquitination (H3K14ub). H3K14ub represents a specific tag for heterochromatin formation by facilitating the deposition of histone H3 trimethylated at 'Lys-9' (H3K9me3). Highly expressed in G2/M phase and associates with mitotic chromosomes in an RNA-dependent manner to catalyze H3K14ub, thereby promoting recruitment of SUV39H (SUV39H1 and/or SUV39H2) and subsequent recruitment of HP1 (CBX1, CBX3 and/or CBX5) proteins to methylated histones.
Synonyms: KIAA1333; FLJ20333; PHF7B
Tractability: PROTAC: ubiquitination databases record sites on it.
Gene: Protein-coding gene on chromosome 14 (30,559,148 to 30,620,064, forward strand). Ensembl gene ENSG00000092140.
Subcellular location: Nucleus; Chromosome; Nucleus, nucleolus; Cytoplasm
Subcellular location (Human Protein Atlas): Cytosol; Golgi apparatus; Vesicles
Gene Ontology:
Molecular function: histone H3K14 ubiquitin ligase activity; protein binding; ubiquitin protein ligase activity; ubiquitin-protein transferase activity
Biological process: heterochromatin formation; pericentric heterochromatin formation; protein localization to chromosome; protein localization to condensed nuclear chromosome; protein ubiquitination
Cellular component: cytosol; pericentric heterochromatin; nucleus; chromosome; cytoplasm; nucleolus
Genetic constraint (gnomAD): Loss-of-function variants: 2 observed, 10.5 expected, observed/expected ratio (o/e) 0.19, 90% interval 0.077 to 0.6. The upper end of that interval is the gene's LOEUF score, 0.6, which puts it in group 2 of 6, group 1 being the genes least tolerant of losing a copy. Missense variants: 46 observed, 75.73 expected, observed/expected ratio (o/e) 0.61, 90% interval 0.48 to 0.78. Synonymous variants: 26 observed, 24.77 expected, observed/expected ratio (o/e) 1.05, 90% interval 0.77 to 1.46.
Homologues: Orthologues: chimpanzee G2E3 (99% identical), macaque G2E3 (98% identical), rabbit G2E3 (91% identical), dog G2E3 (88% identical), guinea pig G2E3 (86% identical), pig G2E3 (84% identical), rat G2e3 (82% identical), mouse G2e3 (79% identical), tropical clawed frog g2e3 (51% identical), zebrafish g2e3 (40% identical), zebrafish si:ch211-57f7.7 (23% identical), Drosophila melanogaster Phf7 (20% identical), and 2 more. Paralogues in human: PHF7 (17% identical), PHF11 (8% identical), PHF6 (8% identical).
Diseases named in the same sentence as G2E3 in open-access papers:
G2E3 is named in the same sentence as 15 diseases in open-access papers, as found by Europe PMC text mining. Sharing a sentence is not in itself a finding about the gene and the disease. The quoted sentences say what the papers report.
breast carcinoma (2 papers, 2021 to 2022). "Following this, we analyzed the relationships between G2E3 expression, tumor immunity, and mutations of G2E3 in breast cancer." (PMID 36517818, 2022). "Using Sanger-box tools, mutations in G2E3 in breast cancer were also explored." (PMID 36517818, 2022). "Finally, we explored the mutation of the G2E3 gene in breast cancer and screened for potential therapeutic compounds that can decrease the G2E3 mRNA expression." (PMID 36517818, 2022). "We further analyzed the relationships between G2E3 expression and age, T grade, N grade, histological grade, subtypes, menopausal status, relapse/metastasis, and death in these 156 patients with breast cancer." (PMID 36517818, 2022). "Immunohistochemistry analysis was utilized to validate the prognostic effect of G2E3 expression in breast cancer patients and the relationship between G2E3 expression and lymphocyte infiltration levels." (PMID 36517818, 2022). "We found that the expression of G2E3 was significantly negatively correlated with lymphocytes infiltration, which was also validated in clinical breast cancer specimens." (PMID 36517818, 2022). "We found G2E3 mRNA expression was significantly higher in breast cancer tissues than in normal tissues (P = 0.003)." (PMID 36517818, 2022). "TCGA and UALCAN database were utilized to explore G2E3 expression in breast cancer and normal tissues and its expression in breast cancer based on clinicopathological characteristics, respectively." (PMID 36517818, 2022). "TCGA data presented that G2E3 expression was higher in breast cancer tissues than in normal breast tissues." (PMID 36517818, 2022). "Using the UALCAN database, we also found the expression of G2E3 mRNA was significantly higher in breast cancer than in normal tissues (P = 1.96E−03)." (PMID 36517818, 2022). "This study primarily analyzed the G2E3 expression in cancerous and normal breast tissues, explored the effect of G2E3 high expression on patient’ survival outcomes, and validated it using clinical breast cancer samples." (PMID 36517818, 2022). "We also found G2E3-positive expression had a high diagnostic value for DFS and OS by ROC curves and was an independent prognostic predictor for DFS in breast cancer patients." (PMID 36517818, 2022). "We further experimentally validated the relationship between G2E3 expression and TILs levels in breast cancer clinical samples." (PMID 36517818, 2022). "Immunohistochemistry analysis of 156 breast cancer clinical specimens also validated patients with G2E3-positive expression had a significantly shorter DFS and OS than patients with G2E3-negative expression." (PMID 36517818, 2022). "In conclusion, we found that G2E3 was more highly expressed in breast cancer tissues than in normal breast tissues." (PMID 36517818, 2022). "First, we validated the expression of G2E3 mRNA in 30 pairs breast cancer and normal tissues by RT-PCR." (PMID 36517818, 2022). "Here, we explored the expression, prognostic significance, and regulatory pathway of G2E3 in breast cancer." (PMID 36517818, 2022). "The Kaplan–Meier plotter database was utilized to determine the effect of G2E3 on the prognosis of breast cancer patients." (PMID 36517818, 2022). "In breast cancer, the G2E3 expression was significantly positively related to the expression of these four methyltransferases." (PMID 36517818, 2022). "We found that (+)-JQ1 compound, 1,2-dimethylhydrazine, and other compounds can decrease the G2E3 mRNA expression, which may be potential therapeutic compounds for breast cancer." (PMID 36517818, 2022). "The expression of G2E3 was similar in all immune subtypes of breast cancer." (PMID 36517818, 2022). "By applying the CTD database, we aimed to screen for potential therapeutic compounds that could decrease the mRNA expression of the G2E3 oncogene in breast cancer patients." (PMID 36517818, 2022).
breast carcinoma (continued). "Therefore, we explored the prognostic significance of G2E3 expression in breast cancer patients and the effect of G2E3 on the malignant biological behavior of cancer cells." (PMID 36517818, 2022). "G2E3 expression was higher in breast cancer tissues than in normal tissues." (PMID 36517818, 2022). "G2E3-positive expression was related to a worse prognosis in patients with breast cancer." (PMID 36517818, 2022). "Finally, potential therapeutic compounds that can decrease the G2E3 mRNA expression in breast cancer were screened." (PMID 36517818, 2022). "G2E3-positive expression was related to a worse survival outcome in patients with breast cancer." (PMID 36517818, 2022). "Therefore, we can conclude that G2E3-positive expression has adverse prognostic effects on the prognosis of breast cancer patients." (PMID 36517818, 2022). "However, the role of G2E3 in breast cancer development and patient’s prognosis is unclear." (PMID 36517818, 2022). "However, the role of G2E3 in breast cancer development and patient’s prognosis is still unclear." (PMID 36517818, 2022). "G2E3 may serve as a novel prognostic biomarker and therapeutic target for breast cancer." (PMID 36517818, 2022). "Genes co-expressed with G2E3 may be enriched in the breast cancer-related signaling pathways." (PMID 36517818, 2022). "We hypothesized that G2E3 could serve as a novel therapeutic target for breast cancer." (PMID 36517818, 2022). "Sanger-box tools also revealed the relationship between G2E3 gene expression and TMB and MSI in breast cancer." (PMID 36517818, 2022). "Thus, G2E3 may serve as a novel prognostic biomarker and therapeutic target for breast cancer." (PMID 36517818, 2022). "We explored the G2E3 expression by immunohistochemistry in 156 breast cancer specimens, presenting as G2E3-positive and -negative cells." (PMID 36517818, 2022). "Second, we did not explore the exact regulatory mechanisms of G2E3 in breast cancer development." (PMID 36517818, 2022). "Finally, we did not determine a relationship between G2E3 expression and breast cancer immunity." (PMID 36517818, 2022).
amyotrophic lateral sclerosis (1 paper, 2021). Amyotrophic lateral sclerosis (ALS) is a neurodegenerative disease characterized by progressive muscular paralysis reflecting degeneration of motor neurons in the primary motor cortex, corticospinal tracts, brainstem and spinal cord. "Moreover, we identified Wald ratio effects between four genes (IQCB, TTC34, MPV17L2 and SLC30A7) and multiple sclerosis risk, and effects between two genes (SCFD1, G2E3) and amyotrophic lateral sclerosis risk." (PMID 33417599, 2021). "For instance, expression levels of G2E3 and SCFD1 not only appear to causally effect the risk for amyotrophic lateral sclerosis but also attention deficient disorder, albeit with alternative directionalities." (PMID 33417599, 2021).
asthma (1 paper, 2020). "Notably, LINC02145 exhibited to be correlated to six asthma-related genes, including ZFN19, G2E3, ATF7IP, PEA15, SPDYE6, VWA5A." (PMID 32948203, 2020).
colon carcinoma (1 paper, 2015).
heart failure (1 paper, 2024). Inability of the heart to pump blood at an adequate rate to meet tissue metabolic requirements. "G2E3 is related to ubiquitin E3 ligases and may contribute to heart failure due to hyper-ubiquitylation and ubiquitin–proteasome system impairment." (PMID 38612670, 2024).
inflammatory bowel disease (1 paper, 2023). A spectrum of small and large bowel inflammatory diseases of unknown etiology. "Currently, little is known about G2E3, and its functions in inflammatory bowel disease or neurodegenerative disorders remain to be explored." (PMID 37163440, 2023).
seminoma (1 paper, 2015). A radiosensitive malignant germ cell tumor found in the testis (especially undescended), and extragonadal sites (anterior mediastinum and pineal gland). "When exploring G2E3 expression in cancerous tissue using the GeneSapiens gene expression database, we found G2E3 expression to be substantially increased in testicular cancer, especially in seminoma." (PMID 25593194, 2015).
cancer (3 papers, 2014 to 2022). A tumor composed of atypical neoplastic, often pleomorphic cells that invade other tissues. "In summary, we introduce G2E3 as a novel modulator of the DDR whose loss sensitizes cancer cells towards DNA damage." (PMID 25593194, 2015). "Moreover, loss of G2E3 triggered apoptosis and decreased proliferation of cancer cells." (PMID 25593194, 2015). "We then obtained the difference in G2E3 expression between cancer tissues and normal tissues in each tumor sample from The Cancer Genome Atlas (TCGA) database." (PMID 36517818, 2022). "Pathway enrichment analysis of G2E3 revealed that it was enriched in “HALLMARK_E2F_TARGETS,” “HALLMARK_PI3K_AKT_MTOR_SIGNALING,” and other cancer-related pathways." (PMID 36517818, 2022). "In the subgroup of individual cancer stages, patients in stage 3 had the highest G2E3 mRNA expression (P = 1.82E−03)." (PMID 36517818, 2022). "This study found G2E3 expression was significantly higher in cancer tissues than in normal tissues, validated using an online database and PCR." (PMID 36517818, 2022). "Finally, in the subgroup of patient subclasses, patients with luminal cancer had the highest G2E3 mRNA expression (P = 1.24E−03)." (PMID 36517818, 2022). "Furthermore, we show that endogenous G2E3 levels in cancer cells were down-regulated upon chemotherapeutic treatment." (PMID 25593194, 2015). "Since depletion of G2E3 decreases Chk1 activity, G2E3 inhibition may sensitize cancer cells in a similar way as Chk1 inhibition, a strategy which has been used in experimental cancer therapy as well as in early clinical studies [reviewed in 39, 40, 41]." (PMID 25593194, 2015). "G2E3 knockdown may promote apoptosis and inhibit cancer cell proliferation." (PMID 36517818, 2022). "Taken together, these results suggest that G2E3 depletion decreases ATR-Chk1 signaling and increases replicative stress in gemcitabine-treated cancer cells." (PMID 25593194, 2015). "Thus, the PHD/RING domains in G2E3 may represent a suitable cancer drug target." (PMID 25593194, 2015). "Our results strongly suggest that G2E3 depletion alleviates ATR-Chk1 signaling and enhances replicative stress in cancer cells." (PMID 25593194, 2015). "GSEA analysis revealed that G2E3 might be enriched in the E2F, PI3K/AKT/mTOR signaling, DNA repair pathways, and other cancer-related signaling pathways." (PMID 36517818, 2022). "Genes co-expressed with G2E3 may be enriched in the E2F and PI3K/AKT/mTOR signaling pathways and other cancer-related signaling pathways." (PMID 36517818, 2022).
tumor (2 papers, 2015 to 2022). "Loss of G2-specific E3-like (G2E3) protein sensitizes tumor cells to chemotherapy." (PMID 36517818, 2022). "The TISIDB database was utilized to determine the relationship between G2E3 expression and tumor immunity." (PMID 36517818, 2022). "Here, Sanger-box tools count the number of neoantigens in every tumor sample and analyze the correlation between G2E3 gene expression and the number of antigens." (PMID 36517818, 2022). "Because there were fewer normal breast samples in TCGA, we further integrated the data of normal breast tissues from the GTEx database and the data of TCGA tumor tissues to analyze the G2E3 expression differences among the 27 tumor types." (PMID 36517818, 2022). "We also explored the relationships between G2E3 expression and the tumor immune microenvironment and tumor neoantigens." (PMID 36517818, 2022). "G2E3 can be a molecular determinant of the DNA damage response (DDR) and cell survival, and its loss of expression can sensitize tumor cells to chemotherapy." (PMID 36517818, 2022). "Simultaneously, the G2E3 expression decreased when tumor cells were treated with chemotherapeutic drugs, such as cisplatin." (PMID 36517818, 2022). "Taken together, our results suggest that G2E3 is a molecular determinant of the DDR and cell survival, and that its loss sensitizes tumor cells towards DNA-damaging treatment." (PMID 25593194, 2015). "Therefore, they concluded that G2E3 might serve as a novel modulator of DDR, and its loss of expression can sensitize tumor cells to DNA damage." (PMID 36517818, 2022). "Finally, endogenous G2E3 levels in tumor cells were reduced upon chemotherapy." (PMID 25593194, 2015).
G2E3 also shares sentences with these, for which no sentence is quoted: multiple sclerosis (1 paper); Obesity (1); osteosarcoma (1); Parkinson disease (1); schizophrenia (1); testicular cancer (1).